MYOF (myoferlin)
Diseases named in the same sentence as MYOF in open-access papers (continued):
Sharing a sentence is not in itself a finding about the gene and the disease.
cardiomyopathy (2 papers, 2019 to 2020). A disease of the heart muscle or myocardium proper. "Here we have presented a clinical case of cardiomyopathy associated with limb-girdle type muscular dystrophy where WES strategy allowed the identification of a truncating variant in myoferlin (MYOF), c.[2576delG; 2575G>C], p.G859QfsTer8." (PMID 31297131, 2019). "In summary, we present a first report of a loss of function MYOF variant in a patient with cardiomyopathy and limb-girdle type muscular dystrophy phenotype." (PMID 31297131, 2019). "However, recently the first case of limb-girdle type muscular dystrophy and associated cardiomyopathy linked to MYOF mutation was described." (PMID 32106631, 2020). "Here, we present an individual with a combination of cardiomyopathy and limb-girdle type muscular dystrophy where whole exome sequencing identified myoferlin (MYOF)—a member of the Ferlin protein family and close homolog of DYSF—as the most likely candidate gene." (PMID 31297131, 2019).
Duchenne muscular dystrophy (2 papers, 2019 to 2020). Duchenne muscular dystrophy (DMD) is a neuromuscular disease characterized by rapidly progressive muscle weakness and wasting due to degeneration of skeletal, smooth and cardiac muscle. "However, myoferlin expression increases in damaged myofibers of the mdx mouse model of Duchenne muscular dystrophy (DMD) and in DMD patients biopsies." (PMID 32106631, 2020).
endometrioid carcinoma (2 papers, 2019 to 2022). "In contrast to these observations, high expression of Myoferlin in endometrioid carcinoma was connected to low-grade tumors, whereas loss of Myoferlin expression led to high-grade carcinomas, presumably because endometrial tissues are steadily undergoing a continuous process of regeneration." (PMID 35330493, 2022).
fibroids (2 papers, 2022 to 2024). "The 3D Hi-C contact frequencies indicate that the risk locus contains 3D chromatin contacts, specifically in leiomyoma patient samples compared to MyoF." (PMID 38326302, 2024). "We performed a clustering analysis of a leiomyoma gene set with the addition of BDNF for MyoF and F samples in both race groups." (PMID 36066972, 2022). "In that study, MyoF transcriptomes appeared more like the transcriptomes of F samples than did the MyoN samples, suggesting that the myometria from women with fibroids were prone to fibroid disease or were affected by the fibroids themselves." (PMID 36066972, 2022).
gastric cancer (2 papers, 2021 to 2022). A primary or metastatic malignant neoplasm involving the stomach. "Taken together, these findings indicated that high expression of MYOF was associated with shorter survival in patients with gastric cancer." (PMID 36147922, 2022). "Disruption of the signaling network between intracellular ROS and myoferlin was associated with reduced migration of gastric cancer cells." (PMID 36147922, 2022). "Myoferlin was found to be more highly expressed in tumor than in normal tissues of gastric cancer patients, with higher expression of Myoferlin associated with shorter survival time." (PMID 36147922, 2022). "Myoferlin was associated with significantly higher intracellular ROS levels and enhanced migration of gastric cancer cells." (PMID 36147922, 2022). "Compared with low MYOF expression, high MYOF expression in patients with intestinal type gastric cancer was associated with significantly poorer OS (HR = 2.73, 95% CI 1.98–3.76, P<0.0001), PFS (HR = 1.88, 95% CI 1.29–2.73, P<0.001) and PPS (HR = 2.05, 95% CI 1.34–3.13, P<0.001)." (PMID 36147922, 2022). "Myoferlin is a candidate prognostic biomarker for gastric cancer and plays an essential role in regulating redox equilibrium and gastric cancer cell migration." (PMID 36147922, 2022). "Because almost all of these signaling pathways and GO terms have been reported to participate in tumor progression, these results suggested the extensive involvement of MYOF in gastric cancer progression." (PMID 36147922, 2022). "The expression of MYOF in gastric cancer cells was further investigated using the Cancer Cell Line Encyclopedia (CCLE) database." (PMID 36147922, 2022). "Compared with normal gastric tissue, the levels of MYOF mRNA were significantly higher in Grades 1 (P<0.05), 2 (P<0.001) and 3 (P<0.0001) gastric cancer tissue, with MYOF mRNA levels increasing with increasing grade of gastric cancer." (PMID 36147922, 2022). "MYOF was found to be highly expressed in most gastric cancer cells, and to be over-expressed in HGC27 and SNU1 cells (P<0.0001 each)." (PMID 36147922, 2022). "Taken together, these findings suggest that myoferlin is a promising prognostic biomarker for gastric cancer, and plays a role in regulating redox equilibrium and migration." (PMID 36147922, 2022). "Moreover, MYOF expression was significantly higher in tumor tissue from patients with N0 (P<0.0001), N1 (P<0.0001), N2 (P<0.001) and N3 (P<0.001) gastric cancer than in normal gastric tissue." (PMID 36147922, 2022). "The ability of MYOF to enhance ROS in gastric cancer cells suggested that alterations in ROS levels could alter the migratory ability of these cells." (PMID 36147922, 2022). "The homeostasis triggered by NAC in MYOF expressing gastric cancer cells suggested tumor-suppressive activity that may be useful clinically in anti-cancer treatment." (PMID 36147922, 2022). "The present study found that MYOF is broadly upregulated in gastric cancer cell lines and patients’ tumor specimens, and that high expression of MYOF could predict relatively poor prognosis in patients with gastric cancer." (PMID 36147922, 2022). "In addition, the effects of myoferlin on intracellular ROS levels and cell migration were assessed in vitro in gastric cancer cells." (PMID 36147922, 2022). "Taken together, these findings suggested that Twist1 and Arpc3 mRNAs are positively regulated by MYOF and that MYOF might promote the motility of gastric cancer cells." (PMID 36147922, 2022). "Myoferlin is highly involved in oxaliplatin resistance and tumor progression in gastric cancer." (PMID 34733798, 2021). "In addition, myoferlin was found to be involved in gastric cancer resistance to oxaliplatin." (PMID 36147922, 2022). "Myoferlin may also be a new target for treatment of patients with gastric cancer." (PMID 36147922, 2022).
gastric cancer (continued). "Moreover, MYOF was found to ameliorate the migratory ability of gastric cancer cells and intracellular ROS levels, whereas the antioxidant NAC could inhibit MYOF-associated cell migration." (PMID 36147922, 2022). "We hypothesized that MYOF could regulate gastric cancer cell migration by altering ROS levels." (PMID 36147922, 2022). "MYOF was found to alter the amounts of GSH and GSSG in gastric cancer cells, reducing the GSH/GSSG ratio in HGC27 and SNU1 cells (P<0.0001)." (PMID 36147922, 2022). "Intracellular ROS levels were found to be higher in MYOF-overexpressing than in control HGC27 (P<0.001) and SNU1 (P<0.0001) gastric cancer cells." (PMID 36147922, 2022). "The MYOF, CLIP1, AHNAK, ANXA2, ITPRIPL2 and LEPROT genes in tissues of patients with gastric cancer were found to be altered by amplification, extensive deletion, truncating mutations, splice mutations, missense mutations, and high/low mRNA expression." (PMID 36147922, 2022). "The mechanism by which myoferlin regulates gastric cancer cell migration and ROS accumulation has not been determined." (PMID 36147922, 2022). "Additional studies are needed to determine whether MYOF regulates MMPs by modulating intracellular ROS levels and whether the antioxidant NAC could block the regulatory cascade in gastric cancer cells." (PMID 36147922, 2022). "DeLong’s tests showed that the efficiency of MYOF was significantly better than that of CLIP1 (P < 0.001) and LEPROT (P = 0.037), and a heatmap showed distinct differences in gene expression profiles between gastric cancer and normal gastric tissue." (PMID 36147922, 2022). "Although MYOF mRNA expression in AJCC stage 1 gastric cancer tissues was no higher than that in normal gastric tissues (P>0.05), the levels of MYOF mRNA were significantly higher in Stages 2 (P<0.0001), 3 (P<0.0001) and 4 (P<0.01) gastric cancer than in normal gastric tissue." (PMID 36147922, 2022). "Myoferlin expression, intracellular ROS levels, the ratios of reduced to oxidized glutathione (GSH/GSSG) and nicotinamide adenine dinucleotide phosphate (NADPH/NADP+) and migratory ability were measured in gastric cancer cells in vitro and in the TCGA and GEO databases in silico." (PMID 36147922, 2022).
malaria (2 papers, 2022 to 2023). Malaria is a serious and sometimes fatal disease caused by a parasite that commonly infects a certain type of mosquito which feeds on humans. "We cannot exclude that beside the effect on HCCU, a part of the growth defect we see after MyoF inactivation arises from similar functions in malaria blood stages." (PMID 38039338, 2023). "The presence of MyosinF (MyoF; PF3D7_1329100, previously also MyoC), in the K13 proxiome could indicate an involvement of actin/myosin in endocytosis in malaria parasites." (PMID 38039338, 2023). "Among the top 50 genes identified in our RNA-Seq experiment, 5 of them (IFNG, CXCL8, IL3RA, SNX10, MYOF, and RSAD2) had promoter regions that were significantly more accessible in convalescent child patients with malaria than in adult convalescent patients." (PMID 35642634, 2022).
Miyoshi myopathy (2 papers, 2019 to 2023). A distal myopathy, characterized by weakness in the distal lower extremity posterior compartment (gastrocnemius and soleus muscles) and associated with difficulties in standing on tip toes. "Dysferlin and myoferlin mutations cause muscle diseases: limb-girdle muscular dystrophy type 2B (LGMD2B), Miyoshi myopathy (Dysferlin), and muscular dystrophy with cardiomyopathy (Myoferlin)." (PMID 37538852, 2023).
nasopharyngeal carcinoma (2 papers, 2021 to 2022). A carcinoma arising from the nasopharyngeal epithelium. "Association between MYOF expression and clinicopathological characteristics in 50 nasopharyngeal carcinoma cases." (PMID 34178975, 2021).
non-small cell lung carcinoma (2 papers, 2025). A group of at least three distinct histological types of lung cancer, including non-small cell squamous cell carcinoma, adenocarcinoma, and large cell carcinoma. "Our findings definitively indicate that TRIM8 constrains the progression of non-small cell lung cancer by facilitating the degradation of MYOF in the cytoplasm via K48-linked ubiquitination." (PMID 39934162, 2025). "While this study provides novel insights into the mechanism by which TRIM8 regulates MYOF to affect the progression of non-small cell lung cancer, the precise role of TRIM8 as a tumour suppressor within the nucleus and its regulation of the MYOF mRNA remain to be elucidated." (PMID 39934162, 2025).
sarcoma (2 papers, 2018 to 2021). A usually aggressive malignant neoplasm of the soft tissue or bone. "We have shown that established Rh30 and RD sarcoma cell lines cultured in the presence of the tested PRMT inhibitors have decreased expression of TNC, NRP1, MYOF, EMP1, OLFML3 and CCND1 and increased expression of the GADD45G gene." (PMID 34360791, 2021).
viral infection (2 papers, 2023). "The viral protein, HBZ, was found to enhance HTLV-1 infection through transcriptional activation of ICAM1 and MYOF, two genes that facilitate viral infection." (PMID 37375521, 2023). "Additionally, we found that MyoF enhances the adhesion properties of the HTLV-1-infected T-cells, which is important, as cell-to-cell contact is essential for viral infection." (PMID 36827461, 2023).
cardiac hypertrophy (1 paper, 2024). "The data indicate that the anti-pyroptosis and cardiac hypertrophy effects of MYOF are associated with NLRP3 inflammatory signaling." (PMID 39553724, 2024). "Additionally, MYOF mitigates pathological myocardial hypertrophy caused by pressure overload by inhibiting the proptosis cascade response." (PMID 39553724, 2024). "Our experiments verified the protective effect of MYOF against TAC-induced pressure overload-induced cardiac hypertrophy." (PMID 39553724, 2024). "Our research demonstrated that MYOF has a beneficial effect in reducing TAC-induced cardiac hypertrophy." (PMID 39553724, 2024). "To clarify the contribution of MYOF to myocardial hypertrophy, we tested the impact of MYOF on overload stimulus-induced myocardial hypertrophy, fibrosis, and heart failure." (PMID 39553724, 2024). "The mouse model used in our study showed that treatment with MYOF resulted in a reduction in myocardial hypertrophy and fibrosis induced by TAC." (PMID 39553724, 2024). "In the future, we will continue to explore the upstream signaling pathways of MYOF to improve cardiac hypertrophy." (PMID 39553724, 2024). "Based on these findings, it can be concluded that MYOF can decrease myocardial hypertrophy by inhibiting pyroptosis." (PMID 39553724, 2024). "To investigate the role of MYOF in cardiac hypertrophy, we conducted a transverse aortic constriction (TAC) experiment in a mouse model." (PMID 39553724, 2024). "The present study aimed to examine the impact of MYOF on pressure overload-induced myocardial hypertrophy and its influence on NLRP3-mediated pyroptosis in an in vivo model of myocardial hypertrophy." (PMID 39553724, 2024). "We found that MYOF can improve cardiac hypertrophy and cardiac function." (PMID 39553724, 2024). "Whether MYOF attenuates heart failure and myocardial hypertrophy by suppressing NLRP 3-mediated pyroptosis remains to be determined." (PMID 39553724, 2024). "Our findings indicate that MYOF is a potential therapeutic agent for cardiac hypertrophy." (PMID 39553724, 2024). "It has been proved that NF- κB may be the upstream signal of the NLRP3 inflammasome, and MYOF may alleviate myocardial hypertrophy by inhibiting the NF- κB signaling pathway." (PMID 39553724, 2024). "MYOF may alleviate cardiac hypertrophy by influencing mitochondria to reduce ROS production." (PMID 39553724, 2024). "However, the role of MYOF in cardiac hypertrophy remains unclear." (PMID 39553724, 2024). "In this study, we established a mouse model of myocardial hypertrophy via TAC and investigated the pathological role of NLRP3 inflammasome-mediated cell pyroptosis, as well as the potential therapeutic effect of MYOF." (PMID 39553724, 2024).
clonorchiasis (1 paper, 2021). Infection of the biliary passages with clonorchis sinensis, also called Opisthorchis sinensis. "However, the function of myoferlin in clonorchiasis, especially its effects on detection sensitivity, has received little attention." (PMID 34733798, 2021). "The sera from rabbits infected with C. sinensis could be probed at different levels, and the sera positive for S. japonica, F. hepatica, and from naive rabbit could hardly be probed, which indicates that myoferlin may be a potential antigen for the detection of clonorchiasis." (PMID 34733798, 2021). "Additionally, myoferlin may be a potential protein for the immunological diagnosis of clonorchiasis." (PMID 34733798, 2021). "Moreover, myoferlin, as a biomarker, may be used to develop an objective method for future diagnosis of clonorchiasis." (PMID 34733798, 2021).
colorectal tumors (1 paper, 2025). "Similarly, the UALCAN website analysis shows that MYOF mRNA is significantly overexpressed in primary colorectal tumors (n = 286) compared to normal colorectal tissues (n = 41, p = 0.0236)." (PMID 39941891, 2025).
COVID-19 (1 paper, 2022). A disease caused by infection with severe acute respiratory syndrome coronavirus 2. "The MYOF (myoferlin) gene modulates VEGF signal transduction, which has already been shown to play a key role in life-threatening COVID-19." (PMID 36552859, 2022).
diabetes (1 paper, 2018). "Myoferlin (MyoF) is a ferlin family member protein located in the plasma and nuclear membrane that plays a major role in VEGFA secretion and causes cardiac muscle weakness in diabetes." (PMID 30212560, 2018).
dystrophinopathy (1 paper, 2021). "Enhanced membrane repair involving myoferlin, dysferlin, and annexins has been found to be accompanied by a robust inflammatory response in the progressive neuromuscular disorder dystrophinopathy." (PMID 34957301, 2021).
follicular lymphoma (1 paper, 2019). Follicular lymphoma is a form of non-Hodgkin lymphoma characterized by a proliferation of B cells whose nodular structure of follicular architecture is preserved. "In follicular lymphoma, MYOF has been identified as a self-antigen that can be recognized by surface BCR of malignant B-cell clone from a patient with follicular lymphoma." (PMID 31828126, 2019).
head and neck cancer (1 paper, 2016). A primary or metastatic malignant neoplasm affecting the head and neck. "However, very little is known about the expression and biological role of myoferlin in head and neck cancer." (PMID 26919244, 2016).
invasive breast carcinoma (1 paper, 2012). A carcinoma that infiltrates the breast parenchyma. "Collectively, these data suggest a potential correlation between MYOF over-expression and invasive breast carcinoma." (PMID 22761893, 2012).
invasive ductal carcinoma (1 paper, 2012). "When MYOF expression was categorized by disease state, we observed significantly higher MYOF mRNA expression in tissues from patients with invasive ductal carcinoma compared with samples from healthy individuals." (PMID 22761893, 2012).
keratoconus (1 paper, 2020). A degenerative, structural disorder of the eye, characterized by a cone-shaped protrusion of the cornea. "The variants in the genes MYOF and STX2 are more likely to be in association with keratoconus because MYOF is calcium/phospholipid-binding protein that plays a role in the plasmalemma repair mechanism of endothelial cells that permits rapid resealing of membranes disrupted by mechanical stress." (PMID 32887565, 2020).
Lewis Lung Carcinoma (1 paper, 2023). "For example, Myoferlin-depleted Lewis Lung Carcinoma cells show a decrease in both migration and proliferation." (PMID 37008019, 2023).
lymph node metastasis (1 paper, 2021). "The immunohistochemical staining scores indicated that the expression levels of MYOF were significantly higher in NPC with lymph node metastasis than without metastasis (p = 0.006)." (PMID 34178975, 2021).
mastitis (1 paper, 2025). Inflammation of breast tissue during lactation or postpartum due to an obstructed duct or infection. "The DCTN1, MYOF, and DPP9 genes encode key regulators of intracellular transport, membrane repair, and protein degradation, respectively, and their expression changes driven by miR-223 suggest a comprehensive modulation of immune response and cellular resilience during mastitis." (PMID 40033327, 2025). "The identification of DEGs and potential target genes, particularly PTPRF, DCTN1, PLEC, MYOF, and DPP9, underscores the critical role of miR-223 in modulating mastitis-related traits in dairy cattle." (PMID 40033327, 2025).
metastatic colorectal cancer (1 paper, 2021). "Therefore, we hypothesized that targeting MYOF may provide a novel therapeutic approach for metastatic colorectal cancer." (PMID 33634965, 2021).
muscular atrophy (1 paper, 2019). The loss of muscle tissue due to inactivity or disease. "In spite of extensive research on muscle disease, little is known about the role of MyoF in muscular atrophy, although MyoF may be a modifier." (PMID 31623157, 2019).
Myocardial fibrosis (1 paper, 2024). "Our experiments showed that compared with the MYOF+TAC group, NLRP3 overexpression can reverse the protective effects of MYOF, increase the proportion of apoptotic cells, the HW/BW ratio, cardiomyocyte cross-sectional area, myocardial fibrosis area, and weaken cardiac function." (PMID 39553724, 2024).